MTHFD2 (methylenetetrahydrofolate dehydrogenase (NADP+ dependent) 2, methenyltetrahydrofolate cyclohydrolase)
Diseases named in the same sentence as MTHFD2 in open-access papers (continued):
Sharing a sentence is not in itself a finding about the gene and the disease.
neuroblastoma (2 papers, 2013 to 2019). Neuroblastoma (NB) is the most common solid, extracranial childhood tumor. "To elucidate the prognostic implications of MTHFD2 and PAICS in neuroblastoma progression, we analyzed the association of MTHFD2 and PAICS expressions with patient survival." (PMID 31624245, 2019). "Next, we examined the MTHFD2/PAICS gene combinations with synergistic effects on neuroblastoma patient survival." (PMID 31624245, 2019). "Poor overall and event-free survivals were found in highly expressed MTHFD2 or PAICS neuroblastoma patients." (PMID 31624245, 2019). "Integrating anti-MYCN ChIP-seq and gene expression profiles of neuroblastoma patients revealed the metabolic enzymes, MTHFD2 and PAICS, required for one-carbon metabolism and purine biosynthesis were concomitantly upregulated, which were more susceptible to metastatic neuroblastoma." (PMID 31624245, 2019). "As in the single knockdown results, shMTHFD2 cells decreased by 49.3%, while that of shPAICS cells decreased by 38.4% compared to shLacZ control, suggesting silencing of MTHFD2 and PAICS had synergistic effect on migration ability in MNA neuroblastoma." (PMID 31624245, 2019). "Dual knockdown of the MYCN-targeted gene pair, MTHFD2 and PAICS, in MNA neuroblastoma cells synergically reduced cell proliferation, colony formation, migration ability, and DNA synthesis." (PMID 31624245, 2019). "The results suggest that the synergistic effect of MTHFD2 and PAICS are related to the biosynthesis of nucleotides, as well as their interconnection in one carbon by folate and purine metabolism in MNA neuroblastoma cells." (PMID 31624245, 2019). "Altogether, the patient survival yielded consistent results as the drug combination assays that simultaneously suppressing MTHFD2 and PAICS expressions showed a synergism in MNA neuroblastoma patients." (PMID 31624245, 2019). "According to the impact of MTHFD2 and PACIS on neuroblastoma patient survival, we ascertain their stimulatory effects on cell proliferation by cell viability and colony formation assays in response to MTHFD2 and PAICS expression manipulation." (PMID 31624245, 2019). "Our dual knockdown and co-treatment assays that target MTHFD2 and PAICS had synergistic effects on MNA neuroblastoma which might diminish the aggressiveness and tumor progression ability." (PMID 31624245, 2019). "To explore the impact of the two metabolic enzymes on MNA neuroblastoma, we first constructed stable knockdown of LacZ (control), MTHFD2, PAICS, and MTHFD2/PAICS (dual-knockdown) by delivering shRNA hairpins into MNA SK-N-DZ cells followed by puromycin selection." (PMID 31624245, 2019). "By systematically screening the compound perturbagens, the gene expression levels of MTHFD2 and PAICS were specifically suppressed by anisomycin and apicidin across cell lines, and our co-treatment results also displayed synergistic inhibition of MNA neuroblastoma cell proliferation." (PMID 31624245, 2019). "Next, we assessed the protein expression levels in six neuroblastoma cell lines, where the MNA cell lines had markedly higher endogenous expressions of MTHFD2 and PAICS compared to non-MNA cell lines." (PMID 31624245, 2019). "We first evaluated the mRNA expression levels of MTHFD2, PAICS, and MYCN in 21 tissue samples from neuroblastoma patients (MNA: n = 9; non-MNA: n = 12)." (PMID 31624245, 2019).
osteosarcoma (2 papers, 2024). A usually aggressive malignant bone-forming mesenchymal neoplasm, predominantly affecting adolescents and young adults. "The finding that MTHFD2 is a prognostic risk gene for osteosarcoma was also demonstrated for the first time in this study." (PMID 38506898, 2024). "Among them, COX6A2, MTHFD2, and NDUFB9 were positively correlated with risk scores, suggesting that they were risk genes for unfavorable prognosis among individuals with osteosarcoma." (PMID 38506898, 2024). "In this research, five oxidative phosphorylation genes linked to the prognosis of individuals with osteosarcoma were screened out, including ATP6V0D1, LHPP, COX6A2, MTHFD2, and NDUFB9." (PMID 38506898, 2024).
ovarian serous adenocarcinoma (2 papers, 2021 to 2022). An adenocarcinoma that arises from the ovary and is characterized by the presence of malignant epithelial cells that, in well differentiated tumors, resemble the epithelium of the fallopian tube or, in poorly differentiated tumors, show anaplastic features and marked nuclear atypia. "MTHFD2 expression was significantly elevated in ovarian mucinous adenocarcinoma, ovarian serous adenocarcinoma, ovarian endometrioid adenocarcinoma than in normal samples." (PMID 35135596, 2022). "The analysis of the Oncomine database revealed fold-changes in gene expression levels that MTHFD2 expression was significantly increased in ovarian mucinous adenocarcinoma, ovarian serous adenocarcinoma, ovarian endometrioid adenocarcinoma compared with normal samples." (PMID 35135596, 2022). "Bioinformatic analysis of the Oncomine microarray gene expression Lu Ovarian dataset, the unpaired tissues from TCGA and GTEx databases showed that the expression level of MTHFD2 mRNA in ovarian serous adenocarcinoma was significantly higher than normal ovarian surface epithelium." (PMID 34231329, 2021).
rectal cancer (2 papers, 2023 to 2025). A primary or metastatic malignant neoplasm that affects the rectum. "Research by Yili Wang and his colleagues discovered that upregulation of miR‐33a‐5p in vitro could target methylenetetrahydrofolate dehydrogenase 2 (MTHFD2) to hold up the growth and migration of rectal cancer cells." (PMID 36125462, 2023).
small cell lung carcinoma (2 papers, 2022 to 2024). Small cell lung cancer (SCLC) is a highly aggressive malignant neoplasm, accounting for 10-15% of lung cancer cases, characterized byrapid growth, and early metastasis. "In addition, miR-30a-3p was recently reported to target MTHFD2 in small cell lung cancer." (PMID 36051358, 2022).
squamous cell carcinoma (2 papers, 2022 to 2024). A carcinoma arising from squamous epithelial cells. "In the TCGA datasets of the two main subtypes of NSCLC, adenocarcinoma (LUAD) and squamous cell carcinoma (LUSC), PSAT1, SHMT1, SHMT2, MTHFD1 and MTHFD2 were significantly overexpressed compared to normal lung tissue." (PMID 38515202, 2024). "Furthermore, the overexpression of MTHFD2 in NSCLC (including adenocarcinoma and squamous cell carcinoma) was also supported by The Cancer Genome Atlas database." (PMID 36051358, 2022).
Arthritis (1 paper, 2026). Inflammation of a joint. "We demonstrate that NFATc1 directly binds the MTHFD2 promoter region, driving metabolic reprogramming in activated T cells from rheumatoid arthritis (RA) patients as well as in experimental arthritis models." (PMID 42270592, 2026).
autoimmune disease (1 paper, 2025). A disorder resulting from loss of function or tissue destruction of an organ or multiple organs, arising from humoral or cellular immune responses of the individual to their own tissue constituents. "In addition, MTHFD2 has been shown to be associated with autoimmune diseases by regulating the fate and function of T cells, providing a new theoretical basis for the research about the subsequent clinical treatment of MM and immunotherapy resistance." (PMID 40280919, 2025).
bone cancer (1 paper, 2022). A primary or metastatic malignant neoplasm affecting the bone or articular cartilage. "In accordance with this, we found that MTHFD2 inhibitors TH7299 and TH9619 are synergistic when combined with ATR inhibitors VE-821 or VE-822 in both AML HL-60 and THP-1 cells, as well as in bone cancer cell lines U2OS and TC71, increasing apoptosis in a time- and dose-dependent manner." (PMID 35228749, 2022).
cleft lip (1 paper, 2023). Congenital defect in the upper lip where the maxillary prominence fails to merge with the merged medial nasal prominences. "Several studies established associations between MTHFD1 and MTHFD2 gene variants and various health conditions such as cancer, cleft lip and palate, Down’s syndrome, and miscarriage." (PMID 37630697, 2023).
COVID-19 (1 paper, 2023). A disease caused by infection with severe acute respiratory syndrome coronavirus 2. "The remaining 8 key genes (EGR2, HIST1H3H, HIST1H4H, HIST1H4I, HIST1H4K, MTHFD2, TUBA4A, and TUBB1) were less studied in the roles of COVID-19 and OA, emphasizing their importance in future research." (PMID 37291167, 2023).
folic acid deficiency (1 paper, 2023). "Previous studies using hen models indicated that folic acid deficiency in hens could significantly increase MTHFD2 gene expression in their offspring, suggesting a potential correlation between maternal FAS and MTHFD2 gene expression in offspring." (PMID 37630697, 2023).
heart failure (1 paper, 2025). Inability of the heart to pump blood at an adequate rate to meet tissue metabolic requirements. "Consistent with the increased heart-to-body-weight ratio of Polg-/mut; Tfam+/+ mice, the expression of Natriuretic Peptide A (Nppa), a marker for heart failure, and Mthfd2 a marker for OXPHOS dysfunction, were increased, whereas there was no change in mRNA levels for Atf4 and Atf5." (PMID 40587199, 2025).
idiopathic dilated cardiomyopathy (1 paper, 2023). Decreased function of the heart associated with cardiac enlargement and congestive heart failure, of unknown cause. "MTHFD2 was also upregulated and in a myocardial sample from one BTHS patient compared with one healthy donor and with two patients with ischemic- or idiopathic dilated cardiomyopathy, respectively." (PMID 37930434, 2023).
metastatic cancers (1 paper, 2025). A carcinoma which has spread from the original site of growth to another anatomic site. "Expanding our understanding of the transport mechanisms and formate-mediated MTHFD2 in nucleotide synthesis may further refine therapeutic strategies targeting formate metabolism in metastatic cancers." (PMID 40756341, 2025).
metastatic disease (1 paper, 2013). "However, in order to get conclusive results on the putative association between high MTHFD2 expression and metastatic disease, additional studies with larger patient cohorts are required." (PMID 23295955, 2013). "Our results showing elevated MTHFD2 expression especially in cancer samples derived from patients with a metastatic disease support in general these conclusions associating NAD dependent methylenetetrahydrofolate dehydrogenase activity with transformed and non-differentiated cells." (PMID 23295955, 2013).
microphthalmia (1 paper, 2023). Congenital or developmental anomaly in which the eyeballs are abnormally small. "A similar search of DR17 using the term microphthalmia resulted in 22 genes significant for the small eyes phenotype: Aldh1a3, Aff4, Bmp4, Cdk4, Cox6b1, Cxcr4, Dync1li1, Eef1d, Fgd1, Gne, Grh12, Mab21l2, Maf, Med13l, Mllt10, Mthfd2, Pex6, Phgdh, Ssr1, Stim1, Tdo2, and Vps26c." (PMID 36737727, 2023).
Mitochondrial myopathy (1 paper, 2017). "It was recently shown that mitochondrial myopathy mouse models with mtDNA replication disorders have increased protein levels of the mitochondrial 1C pathway enzymes MTHFD2 and MTHFD1L, as well as increased transcript levels of the genes encoding for key enzymes of the serine synthesis pathway." (PMID 29132502, 2017).
mucinous tumors (1 paper, 2025). "The expression of MTHFD2 was significantly higher in poorly differentiated tumors compared to well/moderately differentiated or mucinous tumors (p = 0.040) and, once again, was linked to group 1 (p = 0.012)." (PMID 40357991, 2025). "The tumor differentiation grade was linked to expression of MTHFD2 and MFT, with high MTHFD2 expression in poorly differentiated tumors and low MFT expression in mucinous tumors." (PMID 40357991, 2025).
ovarian serous carcinoma (1 paper, 2021). "And MTHFD2 was highly expressed (++ to +++) in 8/10 (80%) cases of metastasis and in 26/62 (41.94%) cases of ovarian serous carcinoma." (PMID 34231329, 2021).
Sepsis (1 paper, 2025). Sepsis is defined as life-threatening organ dysfunction caused by a dysregulated host response to infection. "On the other hand, MTHFD2’s regulatory effect on macrophage and T-cell polarization may trigger immune dysregulation in sepsis, affecting patients’ immune response capacity." (PMID 41424725, 2025). "Our study found that MTHFD2 was significantly overexpressed in neonates with sepsis, suggesting it may play a protective role in the pathological process of NESE." (PMID 41424725, 2025).
systemic lupus erythematosus (1 paper, 2023). An autoimmune multi-organ disease typically associated with vasculopathy and autoantibody production. "Recent research found that MTHFD2 was consistently overexpressed in many diseases, including ulcerative colitis, Celiac’s disease, systemic lupus erythematosus (SLE), psoriatic arthritis, Sjogren’s syndrome, multiple sclerosis (MS) and so on." (PMID 37936908, 2023).
triple-negative breast carcinoma (1 paper, 2023). An invasive breast carcinoma which is negative for expression of estrogen receptor (ER), progesterone receptor (PR), and human epidermal growth factor receptor 2 (HER2). "The present study aimed at elucidating the potential function and mechanisms of MTHFD2 and explored the correlation between ferroptosis and MTHFD2 in triple-negative breast cancer." (PMID 36726381, 2023). "Hence, immune checkpoint inhibitors are promising therapies for MTHFD2-mediated triple-negative breast cancer." (PMID 36726381, 2023).
undifferentiated thyroid carcinoma (1 paper, 2024). "Collectively, we found that SHMT2 and MTHFD2 were significantly associated with low TDS and aggressive clinico-pathological features, supporting the importance of the mitochondrial one-carbon pathway in undifferentiated thyroid carcinoma." (PMID 38331894, 2024).
cancer (150 papers, 2010 to 2026). A tumor composed of atypical neoplastic, often pleomorphic cells that invade other tissues. "In terms of biomarker usage, MTHFD2 is highly enriched in cancers and has been associated with disease prognosis and resistance to therapy." (PMID 41303507, 2025). "It is a rational expectation that inhibition of MTHFD2 can enhance metabolic stresses associated with existing chemotherapeutics such as antifolates, especially in cancers resistant to conventional therapies." (PMID 41303507, 2025). "Does targeting of MTHFD2, therefore, create metabolic deficiencies in cancer cells, or can suppression of the enzyme be compensated by the increased flux through the cytosolic pathway?" (PMID 41303507, 2025). "These include investigating MTHFD2 as a diagnostic and prognostic biomarker by examining its expression patterns across different cancer types and age groups and analyzing its relationship with patient outcomes." (PMID 39668825, 2024). "We propose that targeting MTHFD2 provides a potentially clinically relevant opportunity to selectively introduce HR deficiency in cancer cells, thereby sensitizing repair‐proficient tumors to IR." (PMID 38533616, 2024). "MTHFD2 has garnered attention for its involvement in various cellular processes linked to cancer progression." (PMID 39668825, 2024). "Ultimately, our research elucidates the significant impact of MTHFD2 as a prognostic determinant in cancer, where MTHFD2 deficiency expedites senescence-like alterations to foster tumor growth." (PMID 39668825, 2024). "Together, this indicates that TH9619 causes thymidylate deficiency in MTHFD2-expressing cancer cells by inhibiting MTHFD1(DC), leading to 10-CHO-THF trapping and depletion of THF." (PMID 37012496, 2023). "Mitochondrial MTHFD2 activity supports one-carbon metabolism and redox balance through production of NADPH, and the importance of this activity in cancer cells is underlined by the cancer-specific high MTHFD2 expression." (PMID 37949226, 2023). "Considering the association between MTHFD2, immunoregulators, and immune cell infiltrations in pan-cancer, we then investigated its immune-related biological functions in detail in BLCA." (PMID 38130721, 2023). "MTHFD2, a critical enzyme of folate metabolism, was found to be associated with various malignant features and patients’ prognosis in several cancers." (PMID 38130721, 2023). "TH9619 inhibition of MTHFD1(DC) causes accumulation of the 1C intermediate 10-CHO-THF in MTHFD2-expressing cancer cells (a mechanism we term ‘folate trapping’)." (PMID 37012496, 2023). "We found that inhibition of the DC domain of MTHFD1 by TH9619 causes thymineless death specifically in MTHFD2-expressing cancer cells." (PMID 37012496, 2023). "The role of the MTHFD2 enzyme in causing cancer is explained by its overexpression in the tumour cells and its relation with the patients suffering from cancer." (PMID 37872243, 2023). "In this study, we reveal the complex biological mechanism of action behind TH9619 (and related TH9975) and show how it can be exploited to target both, MTHFD2-overexpressing cancers and cancers deficient in mitochondrial 1C metabolism." (PMID 37012496, 2023). "All these observations indicated that MTHFD2 is tightly associated with the tumorigenesis of various cancer types." (PMID 35581573, 2022). "MTHFD2 is overexpressed in cancer and contributes to genomic instability during the early stages of cancer initiation that are associated with an activated DNA-damage response (DDR)." (PMID 36295863, 2022). "Helleday and colleagues describe a nanomolar MTHFD2 inhibitor that causes replication stress and DNA damage accumulation in cancer cells via thymidine depletion, demonstrating a potential therapeutic strategy in AML tumors in vivo." (PMID 35228749, 2022). "In vitro, cancer cells that lack MTHFD2 are more susceptible to oxidant-induced cell death when MTHFD2 is depleted." (PMID 36358687, 2022).